RNU6-172P (RNA, U6 small nuclear 172, pseudogene)
Gene: Small nuclear RNA gene on chromosome 12 (101,796,410 to 101,796,502, reverse strand). Ensembl gene ENSG00000222932.
Homologues: Orthologues: macaque U6 (91% identical). Paralogues in human: RNU6-737P (82% identical), RNU6-1011P (80% identical), RNU6-1024P (80% identical), RNU6-12P (80% identical), RNU6-13P (80% identical), RNU6-15P (80% identical), RNU6-19P (80% identical), RNU6-32P (80% identical), RNU6-41P (80% identical), RNU6-558P (80% identical), RNU6-767P (80% identical), RNU6-1 (78% identical), and 1283 more.